ELP3 (elongator acetyltransferase complex subunit 3)
Description:
Catalytic tRNA acetyltransferase subunit of the elongator complex which is required for multiple tRNA modifications, including mcm5U (5-methoxycarbonylmethyl uridine), mcm5s2U (5-methoxycarbonylmethyl-2-thiouridine), and ncm5U (5-carbamoylmethyl uridine). In the elongator complex, acts as a tRNA uridine(34) acetyltransferase by mediating formation of carboxymethyluridine in the wobble base at position 34 in tRNAs (By similarity). May also act as a protein lysine acetyltransferase by mediating acetylation of target proteins; such activity is however unclear in vivo and recent evidences suggest that ELP3 primarily acts as a tRNA acetyltransferase. Not a major acetyltransferase of tubulin. Involved in neurogenesis: regulates the migration and branching of projection neurons in the developing cerebral cortex, through a process depending on alpha-tubulin acetylation. Required for acetylation of GJA1 in the developing cerebral cortex (By similarity).
Synonyms: FLJ10422; KAT9
Tractability: Small molecule: a structure with a bound ligand is known. PROTAC: ubiquitination databases record sites on it; its protein half-life has been measured.
Gene: Protein-coding gene on chromosome 8 (28,089,673 to 28,191,156, forward strand). Ensembl gene ENSG00000134014.
Subcellular location: Cytoplasm; Nucleus; Nucleus (Isoform 1); Cytoplasm (Isoform 2)
Subcellular location (Human Protein Atlas): Cytosol
Pathways (Reactome):
Chromatin organization: HATs acetylate histones
Gene Ontology:
Molecular function: acetyltransferase activity; protein binding; tRNA uridine(34) acetyltransferase activity; acyltransferase activity, transferring groups other than amino-acyl groups; catalytic activity; iron-sulfur cluster binding
Biological process: regulation of transcription by RNA polymerase II; tRNA wobble uridine modification; central nervous system development; neuron migration; positive regulation of cell migration; regulation of translation; tRNA wobble base 5-methoxycarbonylmethyl-2-thiouridinylation
Cellular component: cytoplasm; cytosol; elongator holoenzyme complex; nucleolus; nucleus
Genetic constraint (gnomAD): Loss-of-function variants: 48 observed, 65.26 expected, observed/expected ratio (o/e) 0.74, 90% interval 0.58 to 0.94. The upper end of that interval is the gene's LOEUF score, 0.94, which puts it in group 3 of 6, group 1 being the genes least tolerant of losing a copy. Missense variants: 519 observed, 647.1 expected, observed/expected ratio (o/e) 0.8, 90% interval 0.75 to 0.86. Synonymous variants: 195 observed, 228.98 expected, observed/expected ratio (o/e) 0.85, 90% interval 0.76 to 0.96.
Homologues: Orthologues: chimpanzee ELP3 (99% identical), macaque ELP3 (99% identical), dog ELP3 (99% identical), pig ELP3 (99% identical), guinea pig ELP3 (96% identical), rat Elp3 (96% identical), mouse Elp3 (96% identical), rabbit ELP3 (95% identical), tropical clawed frog elp3 (89% identical), zebrafish elp3 (89% identical), Drosophila melanogaster Elp3 (82% identical), Caenorhabditis elegans elpc-3 (79% identical).
Diseases named in the same sentence as ELP3 in open-access papers:
ELP3 is named in the same sentence as 44 diseases in open-access papers, as found by Europe PMC text mining. Sharing a sentence is not in itself a finding about the gene and the disease. The quoted sentences say what the papers report.
amyotrophic lateral sclerosis (14 papers, 2009 to 2024). Amyotrophic lateral sclerosis (ALS) is a neurodegenerative disease characterized by progressive muscular paralysis reflecting degeneration of motor neurons in the primary motor cortex, corticospinal tracts, brainstem and spinal cord. "Variants of the Elp3 gene are associated with motorneuron degeneration and amyotrophic lateral sclerosis (ALS)." (PMID 39958699, 2024). "Allelic variants of ELP3, the catalytic subunit of the Elongator complex, were found to be associated with amyotrophic lateral sclerosis (ALS) in three human populations." (PMID 31213517, 2019). "Recently it has been shown that elp3 was linked to neurodegenerative diseases and more specifically to Amyotrophic Lateral Sclerosis (ALS) in three families." (PMID 20107598, 2010). "Interestingly, allelic variation of ELP3 is associated with the neuromuscular disorder amyotrophic lateral sclerosis (ALS)." (PMID 28167615, 2017). "Furthermore, association studies in humans have revealed that variants at the ELP3 locus confer increased risk for the neurodegenerative disorder Amyotrophic Lateral Sclerosis (ALS)." (PMID 19593383, 2009). "Moreover, it was found that amyotrophic lateral sclerosis (ALS) patients express lower levels of Elp3 in their motor cortex, which is accounted for in proteome impairment." (PMID 33152999, 2020). "Interestingly, three other Elongator subunits, ELP2 to ELP4, have each been associated with CNS disorders: ELP2 and ELP4 have been implicated in intellectual development disorders and epilepsy, and ELP3 with amyotrophic lateral sclerosis." (PMID 28167615, 2017). "Elongator subunit 3 (ELP3) has been identified as a critical factor in modulating the progression of neurodegenerative diseases, notably Amyotrophic Lateral Sclerosis (ALS)." (PMID 39061374, 2024). "Additionally, patients of sporadic amyotrophic lateral sclerosis (ALS) show reduced levels of Elp3 protein and mcm5s2U in the motor cortex." (PMID 30597914, 2018).
breast carcinoma (11 papers, 2017 to 2026). "Diagnostic efficiency of serum Circ‐FAF1 is higher than Circ‐ELP3 and both of them have the appropriate diagnostic value for breast cancer detection." (PMID 34545638, 2021). "They found that hsa_circ_0001785 (Circ‐ELP3) has a high diagnostic value for detecting breast cancer." (PMID 34545638, 2021). "In breast cancer, the oncogenic expression of T protein in multiple oncoviruses can increase the expression of Elp3 and Ctu1/2, promote the translation of DEK oncoproteins, and upregulate the characteristics of the invasion-promoting transcriptome." (PMID 41501031, 2026). "In breast cancer, Elp3 is associated with tRNA modification and the IRES-dependent translation of LEF1 to maintain metastasis in breast cancer." (PMID 41501031, 2026). "The genetic ablation of Elp3 dramatically reduces breast cancer metastases in PyMT-induced breast cancer mouse models and affects cancer cell invasion in a mammary tumor ex vivo culture system." (PMID 38339348, 2024). "For example, serum levels of circ-FAF1 and circ-ELP3 have been proposed as novel potential biomarkers for breast cancer diagnosis." (PMID 39159001, 2024). "For instance, a novel potential biomarker for diagnosing breast cancer was serum Circ‐FAF1/Circ‐ELP3 in one report." (PMID 35792043, 2022). "We designed the present study to investigate the diagnostic efficiency of serum Circ‐ELP3 and Circ‐FAF1, separately and simultaneously, for diagnosis of patients with breast cancer." (PMID 34545638, 2021). "By drawing a ROC curve, we determined the diagnostic values of hsa_circ_0001785 (Circ‐ELP3) and hsa_circ_100219 (Circ‐FAF1) for diagnosis of breast cancer." (PMID 34545638, 2021). "In line with previous studies, we showed that the serum level of hsa_circ_0001785 (Circ‐ELP3) in new cases of breast cancer is higher than control subjects." (PMID 34545638, 2021). "Compared to non‐cancerous controls, Circ‐ELP3 was upregulated in breast cancer patients (p‐value = 0.004)." (PMID 34545638, 2021). "Elongator Acetyltransferase Complex Subunit 3 (ELP3), responsible for mcm5s2 modification, has been found to be upregulated in breast cancer and to facilitate cancer cell metastasis." (PMID 34827123, 2021). "It has been found that approximately 80% of ovarian cancers have DPH1 gene deletions and that ELP3 is up-regulated in breast cancer cells, which in turn leads to increased levels of the oncoprotein DEK." (PMID 28555368, 2017). "Combined measurement of Circ‐ELP3 and Circ‐FAF1 has a high diagnostic value and may be considered a diagnostic biomarker for breast cancer detection." (PMID 34545638, 2021). "It has been suggested that ELP3 could enhance breast cancer metastasis via its role on the wobble uridine (U34) of tRNA modification." (PMID 34545638, 2021). "Circ‐ELP3 is overexpressed in breast cancer serum specimens." (PMID 34545638, 2021). "Furthermore, because of high diagnostic efficiency, Circ‐ELP3 and Circ‐FAF1 could be considered as a potential biomarker for breast cancer detection, especially when used in combination." (PMID 34545638, 2021). "Briefly, our results revealed the high diagnostic value for combined circRNAs panel, including Circ‐ELP3 and Circ‐FAF1 as a non‐invasive marker, in detection of breast carcinomas." (PMID 34545638, 2021). "ELP3, CTU1 and CTU2 are also overexpressed in breast cancer, where they maintain high translation levels of the RNA-binding protein DEK1." (PMID 33564819, 2021). "Subsequently, statistical analysis performed in this study revealed that hsa_circ_0001785 (Circ‐ELP3) has an acceptable diagnostic value (AUC = 0.715, 95% CI = 0.825, 0.595–1.000) as compared to CEA and CA 15‐3 and, therefore, could be considered as a potential biomarker for detecting breast cancer." (PMID 34545638, 2021).
breast carcinoma (continued). "In conclusion, our results revealed an upregulation in Circ‐ELP3 and, in contrast, a downregulation in Circ‐FAF1 in serum specimens of patients with breast cancer while the levels of these circRNAs showed a decrease and an increase values after treatment, respectively." (PMID 34545638, 2021). "Partner enzymes in U34 tRNA modification, including ELP3 and CTU1/2 were found to be up-regulated in human breast cancers and sustain metastasis, through the translation of the oncoprotein DEK, that promotes the translation of the pro-invasive transcription factor LEF1." (PMID 31238876, 2019).
hepatocellular carcinoma (6 papers, 2014 to 2024). A malignant tumor that arises from hepatocytes. "ELP3 has been identified as a signature for hepatocellular carcinoma progression and has been linked to poor prognosis in endometrioid adenocarcinoma." (PMID 25148247, 2014). "The ELP3 protein enhances tumorigenesis by stabilizing c-myc, and ELP3 and c-Myc are overexpressed in hepatocellular carcinoma and colorectal cancer." (PMID 39408909, 2024). "To widely verify the regulatory effect of ELP3 on c-Myc, we also collected the tissues of hepatocellular carcinoma and the adjacent normal tissues from 10 hepatocellular carcinoma patients." (PMID 37771073, 2024). "Some of the ELP members showed differential roles in various cancers, for example, aberrant expression of Elp3 or Elp4 promoted the migration and invasion of hepatocellular carcinoma cells." (PMID 35223903, 2022). "In another study, ELP3 was shown to be upregulated in human hepatocellular carcinoma (HCC) cells, which correlated well with the phosphorylation of protein kinase B (AKT)." (PMID 30597914, 2018). "Moreover, ELP3 and c-Myc were found overexpressed with a positive correlation in colorectal cancer and hepatocellular carcinoma." (PMID 37771073, 2024).
melanoma (6 papers, 2016 to 2024). A malignant, usually aggressive tumor composed of atypical, neoplastic melanocytes. "Additionally, wobble U34 modifications catalyzed by ELP3/CTU1/2 have been shown to drive melanomas that express mutated BRAF, with subsequent resistance to anti-BRAF therapy caused by U34-dependent codon-biased translation of metabolic proteins." (PMID 35327975, 2022). "Although the role of Elp3 in both tumor initiation and progression of epithelial cancers, as well as in the resistance to targeted therapy in melanoma, is well established, its role in the immune response remains poorly studied." (PMID 39085648, 2024). "The enzymatic subunits of the elongator complex ELP1 and ELP3 and the thiolase CTU2 are overexpressed in human melanoma, particularly in melanomas carrying the BRAFV600E mutation." (PMID 33564819, 2021). "ELP1, ELP3, CTU1 and CTU2 are strongly upregulated in BRAFV600E cells and inactivation of ELP3 impaired the development of BRAFV600E melanoma in a zebrafish model." (PMID 30597914, 2018). "Similarly, the development of BRAFV600E-expressing melanoma cells in zebrafish also relies on the elevated expression of Elp3." (PMID 33152999, 2020). "Additionally, silencing of either ELP3 or CTU2 (s 2U) in human melanoma cells resulted in the induction of endogenous protein aggregates, suggesting the effect of Elongator and tRNA thiolation defects on protein solubility to be general and highly likely disease relevant." (PMID 30597914, 2018). "The Elp3-dependent translation of HIF1A protein thus contributes to invasive features and drug resistance in malignant melanoma." (PMID 33152999, 2020). "In a previous study the migration and tumorigenicity of melanoma-derived cells was shown to be significantly decreased upon depletion of ELP1, ELP3, ELP5 or ELP6 in melanoma cells." (PMID 30597914, 2018).
colorectal cancer (3 papers, 2021 to 2024). A primary or metastatic malignant neoplasm that affects the colon or rectum. "ELP3 is also overexpressed in colorectal cancer and it is required for tumour initiation in a WNT-driven colorectal cancer mouse model." (PMID 33564819, 2021). "Furthermore, there is a strong correlation between c-Myc and ELP3 in colorectal cancer." (PMID 37771073, 2024). "In this model, ELP3 transcription is directly increased by WNT, and ELP3-mediated modification of U34 tRNA increases the translation of SOX9, which in turn maintains colorectal cancer stem cells." (PMID 33564819, 2021). "To investigate the clinical relevance of the ELP3 with c-Myc, we isolated tumor tissues with corresponding normal tissues from colorectal cancer patients and analyzed the expression of ELP3 and c-Myc." (PMID 37771073, 2024).
Intellectual disability (3 papers, 2017 to 2023). "Variants in the ELP2 gene are associated with neurodevelopmental (including intellectual) disability while ELP3 variants are associated with ALS, and loss of ELP4 can cause Rolandic epilepsy syndrome and intellectual disability." (PMID 28167615, 2017).
motor neuron degeneration (3 papers, 2011 to 2021). "Microsatellite-based genetic association studies revealed that Elongator complex protein 3 (ELP3) harboring HAT activity is associated with motor neuron degeneration in ALS." (PMID 33419039, 2021). "Elongator has been found to control the migration and differentiation of cortical neurons through acetylation of alpha-tubulin, and variants of the elongator protein 3 (ELP3) gene are associated with motor neuron degeneration in brain tissue of human." (PMID 22216241, 2011). "Several genes mutated in ALS patients and implicated in motor neuron degeneration have been studied in zebrafish, including superoxide dismutase (SOD1), alsin (ALS2), the elongated protein 3 (ELP3), FUS, and TDP-43." (PMID 33499374, 2021).
endometrioid adenocarcinoma (2 papers, 2014 to 2024). An adenocarcinoma characterized by the presence of malignant glandular epithelial cells resembling endometrial cells. "In contrast, the ELP3 protein exhibited high expression in endometrioid adenocarcinoma, and its expression was inversely correlated with progression of the disease." (PMID 39408909, 2024).
Familial dysautonomia (2 papers, 2010 to 2012). "In addition, as human mutationsin Elp3 have been linked to familial dysautonomia, it is likely that the future analysis ofElongator function in model organisms will be of significant preclinicalvalue." (PMID 22645656, 2012).
Airway obstruction (1 paper, 2025). Obstruction of conducting airways of the lung. "Conversely, increased levels of C4M and ELP‐3 in patients with airway obstruction highlight the role of type IV collagen and elastin degradation, primarily driven by PR3 activity rather than NE." (PMID 40760731, 2025).
Alzheimer disease (1 paper, 2025). A progressive, neurodegenerative disease characterized by loss of function and death of nerve cells in several areas of the brain leading to loss of cognitive function such as memory and language. "In neurodegenerative disorders, Alzheimer’s disease (AD) exhibits amyloid pathology-driven disruption of protein homeostasis, linked to reduced ELP3 expression and impaired tRNA modification." (PMID 40565315, 2025).
colitis (1 paper, 2022). Inflammation of the colon. "As Elp3 limits M1 macrophage polarization, we reasoned that Elp3 deficiency in myeloid cells would potentiate phenotypical parameters in a model of experimental colitis." (PMID 35920020, 2022). "As a result, Elp3 deficiency exacerbates intestinal damage in a model of dextran sulfate sodium (DSS)‐driven colitis." (PMID 35920020, 2022). "The capacity of Elp3 to prevent aberrant M1 macrophage polarization defines U34 chemical tRNA modifications as an anti‐inflammatory process as Elp3 deficiency in myeloid cells exacerbates inflammation in a model of experimental colitis." (PMID 35920020, 2022). "Therefore, Elp3 limits the inflammatory response in a model of experimental colitis, at least by blocking M1 macrophage polarization." (PMID 35920020, 2022). "Elp3 expression is downregulated by classical M1‐activating signals in myeloid cells, where it limits the production of pro‐inflammatory cytokines via FoxO1 phosphorylation, and attenuates experimental colitis in mice." (PMID 35920020, 2022).
COVID-19 (1 paper, 2024). A disease caused by infection with severe acute respiratory syndrome coronavirus 2. "Mean serum levels of PC3X (p < 0.0001), PRO-C3 (p = 0.002), C3M (p = 0.009), PRO-FIB (p < 0.0001), CPa9-HNE (p < 0.0001), and ELP-3 (p < 0.0001) were significantly elevated in patients with COVID-19 compared to healthy controls." (PMID 38982423, 2024). "The elevated serum levels of CPa9-HNE and ELP-3 align with these other studies and offer a tool to not only assess the neutrophil count, but neutrophil activity in patients with COVID-19." (PMID 38982423, 2024). "Serum levels of CPa9-HNE and ELP-3 were significantly elevated in patients with COVID-19 as compared to healthy controls which indicate an increased neutrophil activity in patients with COVID-19 at three months after discharge." (PMID 38982423, 2024).
helminth infection (1 paper, 2024). "In this study, we report that Elp3 deficiency in IECs impairs the positive feed-forward type 2 immune signaling circuit triggered upon helminth infection." (PMID 39085648, 2024). "tRNA-modifying enzyme Elp3 is required for protective type 2 immunity in the intestinal epithelium upon helminth infection, supporting tuft cell expansion and goblet cell function." (PMID 39085648, 2024). "This work identifies the tRNA-modifying enzyme Elp3 as a critical promoter of intestinal tuft cell expansion and type 2 immunity in mice, mounting protection against helminth infection." (PMID 39085648, 2024). "As tuft cell expansion occurs upon helminth infection, we subjected both Elp3WT and Elp3ΔIEC mice (i.e. mice lacking Elp3 expression in intestinal epithelial cells) to N. brasiliensis infection." (PMID 39085648, 2024). "We show that epithelial Elp3, a tRNA-modifying enzyme, promotes tuft cell differentiation and is consequently critical for IL-25 production, ILC2 activation, goblet cell expansion and control of Nippostrongylus brasiliensis helminth infection in mice." (PMID 39085648, 2024). "Consistent with an impaired control of worm infection in the intestine of Elp3ΔIEC mice, mRNA levels of the goblet cell marker Retnlβ did not increase upon infection with N. brasiliensis in intestines lacking Elp3." (PMID 39085648, 2024).
immune deficiency (1 paper, 2025). "Through differential analysis, three key genes – GNAQ, ELP3, and TES – were identified as closely linked to processes related to ribosome biogenesis, DNA replication, and congenital immune deficiency." (PMID 39925840, 2025).
intestinal cancer (1 paper, 2017). "ELP3 is induced by Wnt signaling and promotes SOX9 translation, which is necessary for maintenance of intestinal cancer stem cells 38, and SOX9 is upregulated in stem cell population in tongue SCC cells." (PMID 28834425, 2017).